ID4 (inhibitor of DNA binding 4)
Diseases named in the same sentence as ID4 in open-access papers (continued):
Sharing a sentence is not in itself a finding about the gene and the disease.
medulloblastoma (2 papers, 2010 to 2013). A malignant, invasive embryonal neoplasm arising from the cerebellum. "mRNA transcripts for Bdnf (Brain-derived neurotrophic factor), Neurl (Neuralized homolog), Id4 (Inhibitor of DNA binding 4), and Neurod2 (Neurogenic differentiation 2) were up-regulated 5, 3.7, 2.7, and 2.2-fold in SmoA1 +; Pten +/− medulloblastomas." (PMID 20520772, 2010). "Furthermore, in medulloblastoma tissues and cell lines examined (D283 and Daoy), basal ID4 transcript level and protein expression was negligible compared with those of ID3." (PMID 23768125, 2013).
Menke-Hennekam syndrome (2 papers, 2024 to 2025). "Pathogenic variants in the TAZ2, ZZ, and ID4 regions of CBP and p300 are central to genetic classification of Menke-Hennekam syndrome." (PMID 40860344, 2025).
neuroblastoma (2 papers, 2019 to 2021). Neuroblastoma (NB) is the most common solid, extracranial childhood tumor. "Herein, we show by RT-qPCR analysis that ID4 transcript is much more strongly expressed in WT CD56+/CD133− and WT CD56−/CD133+, in comparison with the control neuroblastoma cell line IMR32 that is lacking immunoregulatory properties (unpublished results)." (PMID 33435455, 2021).
ovarian tumour (2 papers, 2011 to 2020). "Studies have identified an inverse correlation between ID4 and BRCA1 mRNA and protein expression levels in breast and ovarian tumour tissue." (PMID 21854619, 2011).
prostatic intraepithelial neoplasia (2 papers, 2013 to 2021). "The prostate in Id4-/- mice have a complex phenotype characterized by attenuated growth and development that also mimics subtle features of prostatic intraepithelial neoplasia (PIN)." (PMID 23786676, 2013).
psoriasis (2 papers, 2015 to 2021). An autoimmune condition characterized by red, well-delineated plaques with silvery scales that are usually on the extensor surfaces and scalp. "Among them, 10 genes including the inhibitor of DNA binding 4 (ID4), heparin binding protein 17 (HBP-17), keratin 16 (KRT16), S100A2, S100A9, S100A12, guanine nucleotide binding protein 15 (GNA15), MTX, PRKMK3, and SCYA2 were all found to be localized in the psoriasis susceptibility loci." (PMID 26362816, 2015).
serous ovarian cancer (2 papers, 2020). "Here, we have defined unique molecular insights into the function of ID4 in BLBC and the related disease high-grade serous ovarian cancer (HGSOC), by combining RIME proteomic analysis, ChIP-seq mapping of genomic binding sites and RNA-seq." (PMID 32527287, 2020).
aplastic anaemia (1 paper, 2020). "Moreover, significantly higher ID4 gene promoter methylation could distinguish MDS from aplastic anaemia, which can be challenging particularly MDS with a low blast count, hypoplasia and/or normal karyotype." (PMID 33114584, 2020).
bladder tumors (1 paper, 2022). "Regarding the ID family genes, the expression of ID2, ID3, and ID4 but not ID1 was significantly lower in bladder tumors than in normal urothelium." (PMID 35729325, 2022).
brain tumors (1 paper, 2010). "Interestingly, the analysis of Id4 protein expression in human GBM specimens evidenced that the majority of Id4-positive cells resides near the vasculature, a location postulated to be the niche for brain tumor stem cells." (PMID 21293053, 2010).
cholesteatoma (1 paper, 2012). A pathologic process characterized by the proliferation of keratinizing squamous epithelium resulting in the accumulation of keratin and cells in the middle ear and/or mastoid. "Moreover, tumor suppressor genes CDH18, 19 and ID4, which are known to be down-regulated in various tumors PAX3, LAMC2 and TRAF2B are also down-regulated in cholesteatoma." (PMID 23285167, 2012).
chronic myelogenous leukemia (1 paper, 2014). "We next explored the embedded “expression” and “regulation” tracks using UCSC genome browser to further explore if in fact histone modifications such as EZH2 mediated H3K27Me3 is observed on ID4 promoter in cells that lack ID4 expression such as chronic myelogenous leukemia cell line K562." (PMID 25115397, 2014).
colorectal adenocarcinoma (1 paper, 2015). The most common type of colorectal carcinoma. "Additionally, CDC42 has been reported to be highly expressed in colorectal adenocarcinoma and downregulate inhibitor of DNA binding 4 (ID4) through an epigenetic mechanism." (PMID 26515597, 2015).
dilated cardiomyopathy (1 paper, 2025). Cardiomyopathy which is characterized by dilation and contractile dysfunction of the left and right ventricles. "ID4 was significantly enriched in the cytosolic DNA sensing pathway and dilated cardiomyopathy, suggesting that it may play a role in the pathology of cytosolic DNA sensing and dilated cardiomyopathy." (PMID 39830966, 2025).
epilepsy (1 paper, 2020). A brain disorder characterized by episodes of abnormally increased neuronal discharge resulting in transient episodes of sensory or motor neurological dysfunction, or psychic dysfunction. "Other potentially relevant genes displaying the same expression trend were the heparan sulfate proteoglycan GPC2 (a marker of immature neurons), the helix–loop–helix transcription factor ID4 (a marker of postmitotic neurons), and the signaling molecule FGFR3 that has been implicated in epilepsy." (PMID 31820119, 2020).
follicular lymphoma (1 paper, 2012). Follicular lymphoma is a form of non-Hodgkin lymphoma characterized by a proliferation of B cells whose nodular structure of follicular architecture is preserved. "For example, ID4 has been shown to act as a putative tumour suppressor gene in AML, DCC is hypermethylated in follicular lymphoma and mutation of TERT increases the risk of familial AML." (PMID 22479372, 2012).
Hyperglycemia (1 paper, 2023). An increased concentration of glucose in the blood. "The results showed that the combination of nicotine and hyperglycemia significantly decreased the mRNA levels of Id1 and Id4 but increased Snail." (PMID 37415117, 2023). "We found that the combination of nicotine and hyperglycemia increased the activation of Smad2/3 and the expression of its target genes Id1 and Id4 but decreased the activation of Smad1/5/8 and the expression of its target gene Snail." (PMID 37415117, 2023).
Intellectual disability (1 paper, 2019).
ischemia (1 paper, 2015). A hypoperfusion of the BLOOD through an organ or tissue caused by a PATHOLOGIC CONSTRICTION or obstruction of its BLOOD VESSELS, or an absence of BLOOD CIRCULATION. "In the ischemia groups, the pattern of ID4 immunoreactivity was similar to that of the sham-operated group." (PMID 25503067, 2015). "In order to identify the cell types of non-pyramidal ID1+ and ID4+ cells, double immunofluorescence staining was performed for ID1/GAD67, ID4/GFAP and ID4/Iba-1 in the hippocampal CA1 region at 5 days post-ischemia." (PMID 25503067, 2015). "In the the CA1 region of the ischemia groups, ID4 immunoreactivity was not changed until 1 day after I-R." (PMID 25503067, 2015). "In summary, these results indicate that immunoreactivity and protein levels of ID1 and ID4 are distinctively altered following transient cerebral ischemia only in the CA1 region, and that the changes in ID1 and ID4 expression may relate to the ischemia-induced delayed neuronal death." (PMID 25503067, 2015).
liver cancer (1 paper, 2017). An epithelial or non-epithelial malignant neoplasm that arises from the liver. "As an important transcriptional regulator, the increased level of Id4 expression may provide a clue regarding the role of Id4 in the development of liver cancer." (PMID 28143562, 2017).
major depression (1 paper, 2017). "Notably, previous studies reported an aberrant increase of the repressor TF ID4 in schizophrenia patient brains and reduction of the OL-specific activator TF SOX10 in the brains of schizophrenia, bipolar, and major depression postmortem cohorts." (PMID 29249816, 2017).
mesothelioma (1 paper, 2018). A usually malignant and aggressive neoplasm of the mesothelium which is often associated with exposure to asbestos. "Among the ID4-dependent angiogenesis-related genes upregulated in macrophages, GRN particularly attracted our attention, because this growth factor is specifically expressed in TNBC and BLBC and has recently been correlated to tumour angiogenesis in mesothelioma." (PMID 29921315, 2018).
metastasis (1 paper, 2022). The spread or migration of cancer cells from one part of the body (where they first appeared) to another. "In addition, ACVR2A, ID1, and ID4 are enriched in the TGF-β signaling pathway, and the role of TGF-β in osteolytic bone metastasis was well known." (PMID 35063044, 2022).
microcephaly (1 paper, 2022). A congenital or acquired developmental disorder in which the circumference of the head is smaller than normal for the person's age and sex. "Because IGFBP2 and ID4 maintain NSCs as well as regulate cerebral and cognitive development, IGFBP2 and ID4 dysregulation during NGLY1-defective cortical development could limit proliferation and cause premature differentiation in NSCs, which may underlie microcephaly in NGLY1-deficiency patients." (PMID 35322011, 2022).
myeloid leukaemia (1 paper, 2017). "To study the potential biological role of ID4 in myeloid leukaemia, we performed proliferation assays and apoptosis assays." (PMID 28452111, 2017). "Epigenetic studies showed that ID4 methylation might be one of the mechanisms silencing ID4 expression in myeloid leukaemia." (PMID 28452111, 2017).
myeloid malignancies (1 paper, 2017). "In the current study, we detected ID4 methylation in a large cohort of myeloid malignancies using RQ‐MSP, a rapid and precise methodology in detecting DNA methylation." (PMID 28452111, 2017). "However, ID4 expression and methylation pattern as well as its direct role in myeloid malignancies were rarely investigated." (PMID 28452111, 2017).
Nicotine addiction (1 paper, 2025). "Among these, the TGF-beta signaling pathway, T cell receptor signaling pathway, and Nicotine addiction pathway were highly enriched (p < 0.01) enriched involving relevant genes (PITX2, ID4, BMP4, DLG1, IKBKB, ICOS, GRIA3, and SLC17A6)." (PMID 40496916, 2025).
oligodendroglial tumor (1 paper, 2005). Oligodendrogliomas are cerebral tumors that are differentiated from other gliomas on the basis of their unique genetic characteristics and better response to chemotherapy. "Id4 expression is present primarily in neoplastic astrocytes in both oligodendroglial tumors and GBM, which is in contrast to the expression patterns of OLIG1 and OLIG2, two survival-associated genes originally identified in GBM tumors." (PMID 16018821, 2005). "In conclusion, we show that Id4 expression is present primarily in neoplastic astrocytes in both oligodendroglial tumors and GBM, which is in contrast to the expression patterns of Olig1 and Olig2, two survival-associated genes originally identified in GBM tumors." (PMID 16018821, 2005). "Because the in silico analysis of tumor specimens cannot distinguish the cellular source of expression, we used immunohistochemistry to localize the expression of Id4 in GBM and oligodendroglial tumors." (PMID 16018821, 2005).
osteoporosis (1 paper, 2010). A condition of reduced bone mass, with decreased cortical thickness and a decrease in the number and size of the trabeculae of cancellous bone (but normal chemical composition), resulting in increased fracture incidence. "The new role of Id4 in promoting osteoblast differentiation renders it a target for preventing the onset of senile osteoporosis." (PMID 20628571, 2010). "The new role of Id4 in directing osteogenic and adipogenic cell fate makes it a likely target for preventing the onset of senile osteoporosis." (PMID 20628571, 2010). "Since BMP and Notch signaling affect osteoblast differentiation at different phases of differentiation, modulation of Id4 expression may create new venues for treating the onset of osteoporosis." (PMID 20628571, 2010).
preeclampsia (1 paper, 2017). Preeclampsia is a hypertensive disorder of pregnancy that is characterized by new-onset hypertension with proteinuria presenting after 20 weeks of gestation, and depending on mild or severe forms may initially present with severe headache, visual disturbances, and hyperreflexia. "In present study, we demonstrated that AAT prevented progression of preeclampsia by enhancing Smad2 phosphorylation and Id4 gene expression." (PMID 29348884, 2017). "We also found that the expression of AAT, Id4 and Smad2 was significantly decreased in preeclampsia tissues compared with normal control, confirming our results in vitro and animal model." (PMID 29348884, 2017). "Reduced Id4 expression and Smad2 phosphorylation were observed in preeclampsia animal model, which was also confirmed in human placenta tissues." (PMID 29348884, 2017). "AAT protected the cells from hypoxia/reoxygenation injury and prevented preeclampsia progress through Id4 that activated by Smad2." (PMID 29348884, 2017). "Here, we identified another Id protein Id4 was dysregulated in hypoxia/reoxygenation injury cells and preeclampsia mice placenta and umbilical vein tissues." (PMID 29348884, 2017). "Preeclampsia resulted in inactivation of Id4 and Smad2, which was re-activated by AAT." (PMID 29348884, 2017). "These phenomena were also confirmed in protein levels evaluated by western blot, suggesting that AAT may through regulating Id4 and Smad2 to contribute to preeclampsia." (PMID 29348884, 2017). "In addition, AAT protected HUVEC cells from hypoxia/reoxygenation injury and relieved preeclampsia symptoms through Smad2/Id4 axis." (PMID 29348884, 2017). "In addition, we collected six normal placenta and preeclampsia placenta tissues from human to examine the expression of AAT, Id4 and Smad2." (PMID 29348884, 2017).
renal carcinoma (1 paper, 2021). A carcinoma arising from the epithelium of the renal parenchyma or the renal pelvis. "In addition, analysis of the R2 public data set shows that ID4 expression is much higher in WT tumors than in normal kidney or renal cancers and that its elevated expression in WT is associated with a poor clinical outcome." (PMID 33435455, 2021). "We found that ID4 is much more expressed in WT tumors than in normal renal tissue or renal cancers." (PMID 33435455, 2021).
retinoblastoma (1 paper, 2022). A malignant tumor that originates in the nuclear layer of the retina. "It has also been reported that miRNA-188-5p was upregulated in retinoblastoma and can promote EMT by targeting ID4 through the Wnt/β-catenin signaling pathway." (PMID 36077718, 2022).
skin cancer (1 paper, 2025). "The expression of ID4 has been reported to be suppressed by UVB irradiation via DNA methylation, which in turn promotes cell proliferation, migration and invasion, contributing to tumor formation in mouse models of skin cancer." (PMID 40296873, 2025).
transient cerebral ischemia (1 paper, 2015). "Additional studies are needed to elucidate the exact role of ID4 in the microglia following transient cerebral ischemia." (PMID 25503067, 2015). "In summary, immunoreactivity and the protein level of ID1 protein were apparently altered in the CA1 pyramidal neurons following transient cerebral ischemia, while ID4 immunoreactivity was detected in the microglia, but not the astrocytes, in the CA1 region following I-R." (PMID 25503067, 2015).
tubular adenoma (1 paper, 2023). A usually polypoid neoplasm arising from the glandular epithelium. "GREMLIN1 expression was significantly upregulated, while the inhibitor of DNA binding (ID) proteins ID1, ID2, ID3 and ID4, all major downstream transcription targets of BMP signaling, were found to be significantly downregulated in serrated adenomas compared to tubular adenomas." (PMID 36326956, 2023).
ulcerative colitis (1 paper, 2025). An inflammatory bowel disease involving the mucosal surface of the large intestine and rectum. "The ID4 lead variant is associated with a large increase in ulcerative colitis risk (p = 1.59 × 10−7, OR = 1.32), providing further evidence that it may play an important role in T1D aetiology." (PMID 39749473, 2025).
X-linked adrenoleukodystrophy (1 paper, 2021). X-linked adrenoleukodystrophy (X-ALD) is a peroxisomal disorder resulting in cerebral demyelination, axonal dysfunction in the spinal cord leading to spastic paraplegia, adrenal insufficiency and in some cases testicular insufficiency. "In addition, in X-linked adrenoleukodystrophy patients, the combination of methylation levels of SPG20, UNC45A, and COL9A3 and also the expression levels of ID4 and MYRF would be a good marker for distinguishing the discriminating childhood from adult inflammatory phenotypes." (PMID 33691689, 2021).